CD4 (CD4 molecule)
Diseases named in the same sentence as CD4 in open-access papers (continued):
Sharing a sentence is not in itself a finding about the gene and the disease.
tumor (17,399 papers, 1990 to 2026). "It has been shown that genetic and epigenetic changes lead to the expansion of neoplastic CD4+ T cells originating from T follicular helper (Tfh) cells, which subsequently cause B cell expansion and tumor development." (PMID 41695367, 2026). "Conditional ablation of SFB-induced IL-17A+CD4+ T cells, precursors of tumour-associated TH1-like cells, abolishes anti-PD-1-mediated tumour control and markedly impairs tumour-specific CD8+ T cell recruitment and effector function within the TME." (PMID 41535459, 2026). "This revealed that a higher proportion of both CD20+DCN+ B cells and CD4+DCN+ T cells interacting with tumour cells was significantly associated with shorter OS." (PMID 41392017, 2026). "Integrated multi-algorithm immune profiling demonstrated that CYP4A22-AS1 was positively linked to tumor purity and resting CD4+ memory T cells, and negatively to immune score and NK cells." (PMID 41614894, 2026). "Higher levels of vitamin D in HNSCC patients are associated with increased infiltration of CD4+ T-cells in the tumor and surrounding stroma, correlating with longer overall survival." (PMID 40934602, 2026). "The presence of CD4+ ICOS+T‐cells in the tumor microenvironment and peripheral blood was associated with a good treatment response to ipilimumab." (PMID 41474629, 2026). "MDSCs, a heterogenous group of mature and immature monocytic and granulocytic lineage cells released from the bone marrow, have long been associated with tumor progression and immune evasion due to their ability to suppress CD4+ and CD8+ T-cell proliferation." (PMID 41541220, 2026). "BRCA1 mutations were associated with CD8+ Trm expansion, whereas BRCA2 mutations were linked to tumor CD4+ Trm expansion and peripheral T/NK cell cytotoxicity." (PMID 42189716, 2026). "IFN-γ promotes CD4 + Th1 cell polarization, and the levels of CD4 + Th1 cells infiltrating the tumor microenvironment are associated with favorable clinical outcomes." (PMID 41582199, 2026). "Activated CD8+ T cells, especially the resident memory effect T cells, predominate in IRF7-C435A mutated tumor, while CD8_Naive and CD4_Naive predominate in IRF7-WT tumors." (PMID 41535256, 2026). "The TIMER results confirmed that in GC, ALDOA is associated with B cells, CD4+ T cells, and macrophages in the infiltrating tumor tissues (P < 0.001)." (PMID 41049005, 2025). "In our study, higher densities of intratumoural CD3+ T cells, CD3+Ki67+ T cells, CD4+ T cells, CD4+Ki67+ T cells were associated with prolonged OS, a strong association consistent with established evidence of T cells in anti-tumour immunity." (PMID 41285059, 2025). "The TME of NSCLC comprises diverse immune cell populations, including CD8 + cytotoxic T cells, CD4 + helper T cells, Tregs, tumor-associated macrophages (TAMs), and dendritic cells (DCs)." (PMID 41262895, 2025). "Previous reports suggest that Jag1 is associated with the acquisition of immune regulatory functions in CD4+ T cells and is also linked to immune evasion within the tumor microenvironment." (PMID 40702356, 2025). "The presence of tumor-specific memory CD4+ T-cells has been linked to improved survival outcomes, highlighting their significance as potential targets for cancer vaccines and adoptive cell therapies." (PMID 40860882, 2025). "By incorporating multiple epitopes from different tumor-associated antigens, MNEVs activate distinct T-cell subsets (CD4+ and CD8+) and B cells, producing a more potent and comprehensive response against cancer cells." (PMID 40453095, 2025). "Then we found it targets tumor through the FXR1-IL-35 axis and causes CD4+ T cells into IL-35-producing induced regulatory T cells (iTr35) to activate anti-tumor immunity to enhance the anti-tumor ability." (PMID 40259042, 2025). "Immune infiltration analyses revealed a significant upregulation of anti-tumor immune cells, including CD4+ T cells and CD8+ T cells, in the low-risk group." (PMID 41323282, 2025).
tumor (continued). "The infiltration of CD8+ and CD4+ T lymphocytes has been implicated in promoting anti-tumor immunity in PDAC." (PMID 39834857, 2025). "One study has found that high total metabolic tumor volume (TMTV) and low tumor-infiltrating (TI) CD4+ cell levels are independently associated with poorer prognosis." (PMID 40270607, 2025). "CIBERSORT-based deconvolution linked FOLH1 to heightened CD8+-T-cell infiltration and showed all three hubs inversely associated with CD4+-T cells, implicating them in shaping the tumor immune milieu." (PMID 40806607, 2025). "Elevated B7-H4 levels are linked to deeper tumor invasion, lymphatic and venous spread, and immunosuppressive effects on CD4+ T cells." (PMID 40739089, 2025). "All five algorithms consistently showed that ITGA4 was markedly associated with immune cell infiltration across various tumors, particularly with tumor-associated macrophages (TAMs), M1 and M2 macrophages, and CD4+ and CD8+ T cells." (PMID 40012546, 2025). "The high-risk group displayed a greater proportion of tumor epithelial cells and endothelial cells, while CD4+ T cells were more abundant in the low-risk group." (PMID 40909272, 2025). "There was a negative correlation between naive B cells and resting memory CD4 T cells in tumor infiltration and risk scores." (PMID 39857718, 2025). "In NSCLCs, the ectonucleotidase CD39 was found to be expressed on tumor cells, tumor-associated endothelial cells, as well as on cells of the immune systems including B-cells, regulatory and activated CD4+ or CD8+ T-cells, and innate immune cells." (PMID 40227655, 2025). "Judging from the box plot, there a significantly lower levels of immune cells with the ability to trigger an inflammatory response and kill tumor cells (including CD4+ T cells, CD8+ T cells, NK cells) in the high-risk subgroup." (PMID 40535819, 2025). "Consisting of diverse immune cells such as CD8+ cytotoxic T lymphocytes (CTLs) and CD4+ helper T cells, they are capable of identifying and eliminating tumor cells by zeroing in on tumor‐associated antigens." (PMID 40673386, 2025). "We observed that enrichment of CD3+CD8– T cells (likely CD4+ helper T cells) was associated with longer five-year overall survival (OS), particularly when they are at the tumour-stroma (peritumoural) interface." (PMID 41459509, 2025). "Flow cytometric analysis of tumor-infiltrating leukocytes revealed that tumors injected with IFNβ-mRNA LNPs were associated with an increased CD8:CD4 T-cell ratio among lymphocytes, more CD69-expressing CD8 T-cells, and an increased presence of M1 macrophages." (PMID 40006725, 2025). "Differently, a spatial association of CD8+ T cells, CD4+ T cells, neutrophils, dendritic cells and TAMs was identified at the tumor-stromal interface and in the KPC model." (PMID 40292277, 2025). "Tumor-associated CD4+ T-lymphocytes show unusual phenotypic plasticity, which enables them to adapt to dynamic conditions within the tissue microenvironment." (PMID 40725022, 2025). "In the “afferent” phase of the immune response, naive CD4+ T cells are stimulated by tumor-associated antigens presented by antigen-presenting cells." (PMID 40176817, 2025). "CD4+ T helper cells can amplify the CTL response against tumor-associated antigens and eliminate malignant cells." (PMID 40302791, 2025). "It is also interesting to investigate the effects of aging and Epas1 deficiency on anti-tumor responses of CD4 T cells." (PMID 39925817, 2025). "They activate the CD8+ and CD4+ T cells of the patient’s own immune system by synthesizing mRNA or DNA to encode tumor-specific neoantigens, thereby achieving precise attacks on tumor cells." (PMID 40733649, 2025). "MSI-H/dMMR tumours have a higher tumour mutational burden that generates an immunogenically “hot” environment, as evidenced by increasing CD4 + and CD8 + lymphocytic infiltration." (PMID 40341577, 2025).
tumor (continued). "Specifically, regular alcohol consumption is associated with lower CD4+ T cell concentrations and poorer tumor differentiation." (PMID 39860614, 2025). "A study demonstrated that during pancreatic cancer progression, tumor-associated microbiota enhanced pro-tumorigenic CD4 T cell activation, which resulted in the production of pro-inflammatory and pro-tumorigenic factors." (PMID 39858007, 2025). "Encapsulating tumor-associated antigens (TAAs) like TRP-1 or gp100 peptides within nanoparticles (NPs) represents a promising approach for eliciting antigen-specific CD4+ T-cell responses." (PMID 40860882, 2025). "XIST is associated with high tumor and peritumoral CD4 inflammation, higher CD25+ cell counts (p=0.01), and elevated intratumoral CD25 expression." (PMID 40352941, 2025). "Studies of patients with NSCLC revealed increased progesterone receptor (PR) to be associated with lower attack of tumor cells by activated CD4+ and CD8+ T cells." (PMID 41463203, 2025). "FRC-like cells were enriched in immune-hot HPV+ve tumours, associated with CD4 + T-cells and B-cells in tertiary lymphoid structures (TLSs), activated by lymphotoxin signalling." (PMID 39757146, 2025). "For example, the adoptive transfer of tumor-specific Tc9s achieves long-term control of tumor growth by activating host CD4+T cells, which is also true in Ag-loss relapsed tumors." (PMID 41009359, 2025). "Typically, tumor-associated Tregs occupy approximately 10%–50% of CD4+ T cells in tumors, which is profoundly greater than that residing in the peripheral blood of healthy individuals (2%–5%)." (PMID 41023740, 2025). "Conversely, RAB5B expression was positively correlated with neutrophil infiltration levels in B cells, tumor-associated fibroblasts, endothelial cells, CD4+ T cells, and mast cells." (PMID 40842984, 2025). "Immunofluorescence assays corroborated these findings, revealing a reduced percentage of CD86+ M1 macrophages and an increased percentage of CD163+ M2 macrophages and CD4+Foxp3+ Treg cells in mutated tumor tissues." (PMID 40384867, 2025). "Evidently, it can be seen that in the context of B2M deficiency, the activation of CD4+ T cells and NK cells can also overcome resistance to exert anti-tumor functions." (PMID 40191187, 2025). "Here, we demonstrated that a high density of FOXP3‐positive cells or a high FOXP3+/CD4+ cell ratio around tumor cells is associated with a poor response to BCG treatment for bladder CIS." (PMID 40084633, 2025). "CD4+ T-lymphocytes are primarily activated by dendritic cells (DCs) presenting tumor-associated antigens in the context of major histocompatibility complex (MHC) class II molecules." (PMID 40725022, 2025). "In this study, we also observed a significant reduction in tumor-infiltrating Tregs (CD4+Foxp3+ T cells) in GSDMD-deficient or DSF-treated mice, presumably due to IL-2 reduction (data not shown)." (PMID 40759573, 2025). "Tumor-associated M2 macrophages and CD4+ CD25+FoxP3+ regulatory T-cells (Tregs) suppress anti-tumor immune responses through secretion of immunosuppressive cytokines IL-10 and TGFβ, and presentation of CTLA4 on T cells and PD-L1 on macrophages." (PMID 40831543, 2025). "In NSCLC, tumor-derived exosomes from patients with any KRAS mutation type induced peripheral blood CD4+ T cell differentiation into Tregs." (PMID 40611261, 2025). "Higher densities of CD3+CD8– (CD4+) T cells were associated with improved five-year overall survival, particularly when enriched at the tumour-stroma boundary (i.e. peritumoural)." (PMID 41459509, 2025). "Although the activated CD4 memory T cells increased in the high-risk group, their function was likely impaired due to exhaustion within the immunosuppressive tumor microenvironment." (PMID 40315269, 2025). "We further show that MYXV can alleviate immune suppression by patient-derived ovarian tumor-associated CD14+ macrophages (TAMs) in coculture with tumor antigen-specific CD4+ T cells." (PMID 40872773, 2025).
tumor (continued). "By contrast, high-risk individuals had more significant proportions of tumor-infiltrating resting memory CD4+ T cells, resting mast cells, and M2 macrophages." (PMID 40535818, 2025). "Patients exhibiting elevated levels of eosinophils, activated natural killer (NK) cells, or naïve CD4+ T cells experienced significantly poorer overall survival (OS), and patients with high tumor mutational burden (TMB) had worse prognosis." (PMID 41287790, 2025). "Specifically, M1 macrophages and activated CD4+ T cells are generally associated with anti-tumor immunity, promoting immune responses against the tumor." (PMID 40699765, 2025). "Concurrently, CD4+ T‐cell clonality reflects tumor antigen heterogeneity; memory and mature CD4+ T cells associate with favorable prognosis, whereas increased regulatory T cells (Tregs) predict poor outcomes." (PMID 40356222, 2025). "The principal components of the TME include tumor-associated macrophages (TAMs), tumor-associated neutrophils (TANs), regulatory T cells, CD4+ T cells, and dendritic cells." (PMID 40332367, 2025). "Cytotoxic CD8+ T cells, along with certain subsets of CD4+ T cells (such as Th1, Th2, and cytotoxic CD4+ cells), are particularly associated with potent anti-tumor immunity." (PMID 40427188, 2025). "This process is characterized by several stages: uptake of MHC II molecules, intracellular trafficking of MHC II molecules, uptake and degradation of tumor-associated antigens, peptide loading, and the activation of CD4+ T cells." (PMID 41361104, 2025). "Based on canonical marker gene expression, eight cell types were identified through unbiased clustering: tumour cells, endothelial cells, cancer‐associated fibroblasts (CAFs), CD4+ T, CD8+ T, natural killer, plasma/B and myeloid cells." (PMID 40052383, 2025). "Co-culture experiments showed that TBX21-deficient tumor cells reduced the induction of CD25+Foxp3+ Treg cells from activated CD4+ T cells." (PMID 41573646, 2025). "Tumor with high-risk scores tended to be in a status of relatively high tumor infiltration of CD4+ T cells, neutrophils, and macrophages, while tumor with low-risk scores tended to be in a status of relatively high tumor infiltration of CD8+ T cells." (PMID 40182754, 2025). "Engaging multiple immune effector arms, including anti-tumor neutrophils recruited during CD4+ T-cell therapy, can help eliminate antigen-loss variants that arise." (PMID 41567982, 2025). "An evaluation of T cell function in LKB1-deficient tumours revealed significantly less IFNg and Ki-67 expression in CD4+ and CD8+ tumour-infiltrating T cells." (PMID 40647497, 2025). "PD-1 expression is also documented in T-cells surrounding tumor cells in nodular lymphocyte-predominant HL and on CD4+ T-cells in HTLV-1-associated adult T-cell leukemia and lymphoma." (PMID 40723175, 2025). "Cxcl9 and cCxcl10 play a crucial role in the recruitment of cytotoxic CD8 + T cell and Th1 CD4 + T cell into the tumour site, and are generally associated with better prognosis and enhanced response to Immunotherapy." (PMID 40316725, 2025). "Characterization of B cell subsets identified tumor-associated atypical B cells (TAABs) with significant clonal expansion and proliferation, linked to activated CD4 + T cells." (PMID 41035074, 2025). "The staffs designed a tumor-associated antigens (TAAs)-based personalized DC vaccine to enhance the CD4+ and CD8+ T cells in Glioblastoma multiforme and NSCLC." (PMID 40216744, 2025). "The expression of UNC5A was associated with tumor purity (r = − 0.143), CD4 + T cells (r = 0.184), macrophages (r = 0.169), neutrophils (r = 0.189), and dendritic cells (r = 0.117)." (PMID 41407823, 2025).
tumor (continued). "In the high-risk PUM tumors, a high intratumoral CD8/CD4 ratio was seen (mean 2.66 in tumor vs. 0.70 in blood; P = 5.1 × 10−6)." (PMID 39918475, 2025). "Reduced tumor-infiltrating CD4+ T lymphocytes (CD4+ TILs) are associated with poor prognosis in HCC." (PMID 40699668, 2025). "Some studies have indicated that CD8+ cells play a pivotal role as immune cells in tumor elimination, while CD4+ T cells contribute to the immune response and are linked to improved prognosis." (PMID 40729021, 2025). "These immunosuppressive cells mainly include myeloid-derived suppressor cells (MDSCs), tumor-associated macrophages (TAMs), and regulatory CD4+ T cells (Tregs)." (PMID 40006624, 2025). "This ex vivo expansion induce a Th1/Th17 phenotype switch of CD4+ T cells which when injected into mice caused reduced tumor progression compared to the respective experimental controls." (PMID 40563574, 2025). "The use of ICIs is caused by the fact that EC tumor cells are characterized by overexpression of PD-L1 and PD-L2 ligands in relation to PD-1 receptors, located on the surface of CD4+/CD8+ T lymphocytes, which infiltrate this tumor." (PMID 41375669, 2025). "Among them, EP26 displayed the highest inhibitory activity, promoting cell death in vitro and inhibiting tumor growth in vivo, associated with increased CD4+ and CD8+ T cells in TME, which was more effective than gefitinib and PD‐L1 inhibitor P19." (PMID 40859900, 2025). "They demonstrated that SUV39H2 loss enhanced oHSV-1 anti-tumor activity and increased intratumoral CD4 and CD8 T-cell infiltration." (PMID 41463023, 2025). "In particular, tumor-associated AtM B cells are characterized by high levels of clonal expansion and proliferation, as well as close interactions with activated CD4+ T cells in tumors, which can predict the immunotherapy response." (PMID 39744696, 2025). "Cinobufagin effectively induced PANoptosis, leading to increased immunogenic cell death, facilitated tumor-associated microglia/macrophages (TAMs) polarization towards an M1-like phenotype while augmenting CD4+/CD8 + T cell infiltration and activation." (PMID 39901195, 2025). "Specifically, QUE’s drug combination inhibited CD4+T cells differentiate to Th2, tumor-associated neutrophils differentiate to N2 type, and tumor-associated macrophages differentiate to M2 type." (PMID 40491926, 2025). "Despite impaired CD4+ T cell activation, Atg5 deficiency in activated CD4+ T cells led to an enhanced anti-tumor response." (PMID 40977681, 2025). "Increased total and stromal CD3+ and CD4+ T cells were positively associated with higher tumor malignancy grade." (PMID 41150099, 2025). "Bispecific antibody-conjugated nanoparticles that target both CD4+ and tumor-associated antigens enhance immune synapse formation and amplify T-cell cytotoxicity." (PMID 40860882, 2025). "In contrast, high‐risk patients showed increased activated CD4 memory T, M2 macrophage and neutrophil infiltration, which potentially correlated with immunosuppression and tumour progression." (PMID 40842081, 2025). "The tumor immune microenvironment is mainly composed of cells such as CD8+ T cells, CD4+ T cells, dendritic cells (DC), natural killer cells (NK), myeloid-derived suppressor cells (MDSCs), tumor-associated macrophages (TAMs) and regulatory T cells (Tregs)." (PMID 40296912, 2025). "In contrast, other complement proteins, such as C3a and C5a, act as allergenic toxins that promote tumor metastasis and tumor-associated angiogenesis by activating CD4+ T cells." (PMID 40255905, 2025). "The results revealed that a higher expression of BUB1B in OC tissues was associated with a higher proportion of tumor cells; moreover, infiltration of CD4 T+ cells, macrophages, and neutrophils also showed an increasing trend." (PMID 41163302, 2025). "These DCs then process and present tumor-associated antigens (TAAs) to CD4+ T cells within regional lymph nodes, initiating T cell activation." (PMID 41264121, 2025).